GPX1P1 (glutathione peroxidase pseudogene 1)
Synonyms: formerly GPXL2; GPXP1
Gene: Transcribed processed pseudogene on chromosome X (13,378,735 to 13,379,340, reverse strand). Ensembl gene ENSG00000197582.
Diseases named in the same sentence as GPX1P1 in open-access papers:
GPX1P1 is named in the same sentence as 2 diseases in open-access papers, as found by Europe PMC text mining. Sharing a sentence is not in itself a finding about the gene and the disease. The quoted sentences say what the papers report.
nasopharyngeal carcinoma (1 paper, 2024). A carcinoma arising from the nasopharyngeal epithelium. "Of particular interest are the genes CYP4F24P and GPX1P1, both long non-coding RNAs, which are implicated in nasopharyngeal cancer." (PMID 39315271, 2024). "Investigating whether individuals with naturally switched-off GPX1P1 and CYP4F24P are at a higher risk of nasopharyngeal cancer will enable genotyping to identify individuals at elevated risk for nasopharyngeal cancer, facilitating early interventions and improving patient outcomes." (PMID 39315271, 2024).
GPX1P1 also shares sentences with these, for which no sentence is quoted: colorectal cancer (1 paper).